F11R (F11 receptor)
Diseases named in the same sentence as F11R in open-access papers (continued):
Sharing a sentence is not in itself a finding about the gene and the disease.
rheumatoid arthritis (2 papers, 2022). A chronic, systemic autoimmune disorder characterized by inflammation in the synovial membranes and articular surfaces. "Accordingly, a previous study showed upregulation of the F11R gene encoding JAM-A in peripheral blood mononuclear cells from patients with rheumatoid arthritis, a condition characterized by high IL1β release." (PMID 36531986, 2022).
allergic disease (1 paper, 2017). An immune response that occurs following re-exposure to an innocuous antigen, and that requires the presence of existing antibodies against that antigen. "Some of these genes have a known function that is relevant to allergic disease, including F11R, CD247, PGAP3, AAGAB, CAMK4 and PEX14, and so could be prioritized for functional follow-up." (PMID 29333270, 2017).
cholestatic cirrhosis (1 paper, 2023). "Finally, in a one-year-old (now 8y) Roma girl (ID F1RO453) with cholestatic cirrhosis, WES revealed a yet unreported homozygous splice-site variant, c.65-2A>T, in F11R (OMIM 605721), encoding the tight junction protein JAM1." (PMID 37471416, 2023).
Cholestatic liver disease (1 paper, 2023). "Since F11r-/- mice are highly susceptible to liver injury and since deficiency of other tight junction proteins, namely tight junction protein 2 and claudin-1, is associated with cholestatic liver disease, to explain the proband ́s phenotype as a consequence of JAM1 deficiency tempted us." (PMID 37471416, 2023).
clear cell renal cell carcinoma (1 paper, 2022). "Nonetheless, F11R/JAM-A expression in biopsies of patients with clear cell renal cell carcinoma is associated with primary tumor category and tumor grade." (PMID 34533648, 2022).
E. coli infection (1 paper, 2020). "Six genes (CLDN20, PARD6B, CD151, CDH11, CLDN2 and F11R) related to the GO biological process “Cell junction organization” were upregulated by E. coli infection, whereas these genes were not induced by EPS." (PMID 32234079, 2020).
leukemia (1 paper, 2023). A malignant (clonal) hematologic disorder, involving hematopoietic stem cells and characterized by the presence of primitive or atypical myeloid or lymphoid cells in the bone marrow and the blood. "As quality control of the system, transduction of leukemia cell lines expressing split-Cas9 with sgRNAs targeting CD19, CD81 or F11R strongly decreased the expression of the respective cell surface proteins." (PMID 37422628, 2023).
malignant glioma (1 paper, 2013). A grade III or grade IV glioma arising from the central nervous system. "Third, we show that one of these differentially-expressed transcripts, F11R, serves as a unique predictive biomarker for malignant glioma." (PMID 24147027, 2013).
mastitis (1 paper, 2020). Inflammation of breast tissue during lactation or postpartum due to an obstructed duct or infection. "Additionally, some of the highly connected genes belonging to this module have been found by others to be related to mastitis development, immune response or mammary gland development including FYN, CDH11, CAV1, F11R, ZEB1, ERBB2, and ERBB3." (PMID 32754201, 2020).
serous retinal detachment (1 paper, 2020). "Since F11 receptor seems to be implicated in the maintenance of retinal pigment epithelium barrier, we then checked whether DME patients showing serous retinal detachment (SRD) at OCT examination showed also miR-199a-3p differential expression levels in AH respect to those not showing any SRD." (PMID 33023063, 2020).
steatosis (1 paper, 2021). Increased lipid within the cytoplasm of cells. "Animals fed an HFD are more prone to develop non-alcoholic steatohepatitis (NASH) and steatosis when they are subjected to deletion of F11r, a gene that encodes for the TJ junctional adhesion molecule A (JAM-A) protein." (PMID 34886561, 2021).
uterus cancer (1 paper, 2023). "The most pronounced increase of F11R expression was noticed for breast, testis, and uterus cancer." (PMID 37563645, 2023).
tumor (74 papers, 2010 to 2026). "Intensified tumor growth, cancer cell proliferation, and microglia activation (Fizz1 and Ifi202b anti-inflammatory gene overexpression) were observed in female mice with F11R/JAM-A deficiency." (PMID 34533648, 2022). "For example, a monoclonal antibody (mAb) against F11R/JAM-A inhibited tumor growth in several mouse models." (PMID 37563645, 2023). "Two of the three tumor-infiltrating neutrophil states showed relatively high expression of F11r mRNA despite low overall JAM-A protein expression in neutrophils." (PMID 36531986, 2022). "The crucial role of F11R/JAM-A in the female tumor microenvironment is to diminish microglial activation." (PMID 34533648, 2022). "F11R/JAM-A suppression promotes the cell cycle arrest at the G1/S boundary, thereby decreases cancer cell proliferation and tumor growth." (PMID 34533648, 2022). "F11R mediates the formation of tight junctions between the epithelium and endothelium and participates in the invasion and metastasis of tumor cells." (PMID 35295710, 2022). "This complex increases the expression of downstream proteins, such as vav guanine nucleotide exchange factor 3/F11 receptor, and ultimately leads to tumor progression and a poorer tumor prognosis." (PMID 35465324, 2022). "It is necessary to explore in detail the clinical significance and biological roles of F11R in carcinogenesis and tumor progression." (PMID 35295710, 2022). "Revealed F11R/JAM-A overexpression was related to cancer cell perineural invasion, aggressive histological tumor grades, and correlated with a low survival rate in comparison to cancer patients with F11R/JAM-A underexpression." (PMID 34533648, 2022). "Similarly, expression of the microglia homeostatic genes P2RY12 and CX3CR1 declined with tumor grade, while expression of the immunosuppressive genes IL10 and F11R (JAM-A) increased with tumor grade." (PMID 38895459, 2025). "The expression level of F11R gene was distinctly elevated in tumour tissues." (PMID 37563645, 2023). "Taking into consideration F11R/JAM-A’s pivotal role in leukocyte trafficking, it is important to determine its significance in leukocyte infiltration into the tumor microenvironment, which may be used in cancer immunotherapy." (PMID 34533648, 2022). "However, some research groups have tried to study the role of F11R gene expression in tumor progression." (PMID 35295710, 2022). "F11R/JAM-A overexpression positively correlated with tumor aggressiveness and NSCLC progression." (PMID 34533648, 2022). "F11R is overexpressed in tumor tissues and promotes biological processes in HNSCC." (PMID 35402226, 2022). "Besides, an anti-F11R/JAM-A monoclonal antibody treatment inhibited tumor progression in vivo in MM-bearing mice." (PMID 34533648, 2022). "Knockdown of F11R/JAM-A was associated with intensified apoptosis of cancer cells, reduced in vivo tumorigenicity, attenuated colony-forming ability, decreased motility and invasiveness of cells, while increased expression was related to neoplasia occurrence." (PMID 34533648, 2022). "Strikingly, the levels of plasma sJAM-A and EC-expressed JAM-A protein were reduced by the tumor inducers Tβ4 and TGF-β1, and the F11R/JAM-A antagonistic peptide 4D (P4D) showed a prospective barrier-protecting effect." (PMID 35872908, 2022). "As metastasis is a key event in tumor progression and is responsible for most deaths in cancer patients, the migrating ability of PANC-1 cells with F11R gene knockdown was explored." (PMID 35295710, 2022). "In the tumor microenvironment (TME), F11R/JAM-A expression is also high in cells like macrophages and microglia." (PMID 34533648, 2022). "Transcriptional profiles of circulating tumour cells from 5 different cancer types revealed conserved upregulation of PECAM‐1, JAM3 (JAM‐C) and F11R (JAM‐A), which are critical for leucocyte diapedesis." (PMID 33210465, 2020).
tumor (continued). "The tumor inducers Tβ4 and TGF-β1 reduced the levels of sJAM-A in murine plasma, and reduced the F11R/JAM-A protein levels in the human microvascular endothelial cell line HMEC-1." (PMID 31650345, 2020). "Immunohistochemistry of 77 specimens of human SGTs and 40 non-tumorous tissues revealed the high F11R/JAM-A expression in ductal epithelium tumor cells compared to normal tissues." (PMID 34533648, 2022). "Tumor inducers Tβ4 and TGF-β1 decrease the plasma levels of soluble F11R/JAM-A." (PMID 31650345, 2020). "F11R, as we have analyzed above, has been confirmed to have a relatively low expression pattern in the PDX tumor tissue derived from soft tissue, which is somewhat different from those derived from other tissues, validating the accuracy and efficacy of this rule." (PMID 31456818, 2019). "Furthermore, an unfavorable clinicopathological feature in EOC is related to advanced International Federation of Gynecologists and Obstetricians (FIGO) stage, peritoneal metastasis, residual tumor, and high F11R/JAM-A expression, suggesting the F11R/JAM-A involvement in tumor aggressiveness." (PMID 34533648, 2022).
cancer (63 papers, 2010 to 2026). A tumor composed of atypical neoplastic, often pleomorphic cells that invade other tissues. "The F11R/JAM-A function in cancer progression is not only associated with the regulation of cell migration but also with an influence on apoptosis and proliferation." (PMID 34533648, 2022). "Migration of cancer cells induced by miR-495 is associated with high F11R/JAM-A level." (PMID 34533648, 2022). "These cells leverage F11R/JAM1‐mediated intercellular junctions through JAM3 interactions with cancer and stromal cells, potentially establishing physical exclusion zones that limit immunocyte infiltration." (PMID 41057994, 2025). "By contrast, positive effects have been achieved though F11R downregulation, which comprise counteraction of cancer progression." (PMID 38662188, 2024). "Previous studies have shown that the characterized two markers (F11R and PTGIR) are associated with cancer progression, epithelial-mesenchymal transition (EMT), or metastasis." (PMID 38375422, 2024). "Based on online databases analysis, the aberrant expression of F11R/JAM-A cell adhesion molecule is characteristic for most types of cancer." (PMID 37563645, 2023). "We also discuss the correlation between poor cancer patient clinical outcomes and aberrant F11R/JAM-A expression." (PMID 34533648, 2022). "In parallel, it was shown that the miR-124 overexpression intensified radiosensitivity and suppressed stem-like properties of cancer cells through F11R/JAM-A targeting." (PMID 34533648, 2022). "In this review, we focus on the dysregulation of a TJ protein, namely F11R/JAM-A, and its contribution to human cancer progression and metastasis." (PMID 34533648, 2022). "Regarding the underlying mechanism, the high F11R/JAM-A level initiated the TGF-β/NODAL signaling, whereby prompted increased cancer cell aggressiveness." (PMID 34533648, 2022). "In in vitro studies, cancer cell proliferation, transendothelial migration, and motility were dampened after the restoration of the F11R/JAM-A protein level." (PMID 34533648, 2022). "Moreover, P4D blocks the interactions of F11R/JAM-A molecules relocated upon inflammation from endothelial TJs to the apical endothelial surface with the F11R/JAM-A molecules present on cancer cells, therefore P4D inhibits the early stages of metastasis." (PMID 37563645, 2023). "Functional approach coupled with proteomic analysis permitted to identify F11R/JAM-A as a promising cancer drug target in conjunction with observations that F11R/JAM-A can serve as a cell surface marker for high-throughput flow cytometry-based characterization of TNBC cancer stem cells (CSCs)." (PMID 37563645, 2023). "For example, F11R/JAM-A was reported to be important for self-renewal in TNBC cancer stem cells." (PMID 37563645, 2023). "F11R/JAM-A participation in cancer progression and invasiveness is still a debated issue." (PMID 34533648, 2022). "Therefore, it is suggested that F11R/JAM-A-mediated dendritic cell migration plays a role in cancer progression by indirect influence on the immune response." (PMID 34533648, 2022). "F11R/JAM-A could be a prognostic value in cancer progression because its low expression level negatively correlates with the presence of distant metastasis, histologic grade, and positive lymph node status." (PMID 34533648, 2022). "In the future, it will be required to clarify the signaling pathways that are activated or suppressed via the F11R/JAM-A protein in various cancer types to understand its multiple roles in cancer progression and further use it as a novel direct target for cancer treatment." (PMID 34533648, 2022). "Junctional adhesion molecule-A (JAM-A), also known as F11 receptor (F11R), is a transmembrane glycoprotein that is involved in various biological processes, including cancer initiation and progression." (PMID 39061997, 2024).
cancer (continued). "A recent report describes that the antibiotic against Gram-positive bacteria Tetrocarcin-A, that was noted for the induction of apoptosis in cancer cells, can be a potential novel drug for TNBC treatment due to its antagonistic properties towards F11R/JAM-A." (PMID 37563645, 2023). "First published studies concerning the F11R/JAM-A expression in MM patients reported high F11R/JAM-A expression in primary cells and cancer cell lines (RPMI-8226, U266, NCI-H929, LP-1, KMS-12-BM, SKMM-2, OPM-2)." (PMID 34533648, 2022). "Thus, the endothelial permeability is increased and F11R/JAM-A actively promotes the adhesion and the subsequent transendothelial migration (TEM) of leukocytes and cancer cells." (PMID 37563645, 2023). "Therefore, we have developed the peptide antagonist to F11R/JAM-A, designated as peptide 4D (P4D), that mimics the trans-homodimerization interface of F11R/JAM-A molecule, thus binding to this active site and blocking the interactions of endothelium with leukocytes and cancer cells." (PMID 37563645, 2023). "Interactions between junctional adhesion molecules (JAMs), including F11R, JAM2, and JAM3, are identified, and while their role during AV development is unknown, they are essential drivers of EMT in the context of cancer metastasis, modulating morphology, migration, and cell polarity." (PMID 37689753, 2023). "Importantly, myCAFs might take advantage of F11R (also called JAM1, junctional adhesion molecule 1) to form tight junctions with cancer and stromal cells through F11R and JAM3, which might prevent the infiltration of immunocytes." (PMID 35986392, 2022).
infection (36 papers, 2009 to 2026). The state of being infected such as from the introduction of a foreign agent such as serum, vaccine, antigenic substance or organism. "However, G9P infection of PIEs led to a significant upregulation of tight junction protein JAM-A—F11R, while the expression of the hsc70 protein-encoding gene was downregulated." (PMID 37515094, 2023). "Interestingly, expression of TJP1, F11R, OCLN and CLDN5 were transiently increased after 2 or 4 days of infection before their downregulation (median increase up to 28.4% for TJP1, 33.5% for F11R, 110.4% for OCLN and 51.6% for CLDN5)." (PMID 37537664, 2023).
cardiovascular diseases (6 papers, 2011 to 2024). "F11R/JAM-A derived peptides were previously applied for the drug development in the cardiovascular disorders treatment." (PMID 31650345, 2020).
brain disorder (1 paper, 2025). A disease affecting the brain or part of the brain. "Of the significant reverse MR relationships, the brain disorders demonstrated associations with the increased expression of six proteins (PAMR1, MAVS, F11R, REN, GER and LEPR) and decreased expression of three proteins (TNFRSF4, BTN2A1, ENPP6)." (PMID 40456753, 2025).
F11R also shares sentences with these, for which no sentence is quoted: colitis (24 papers); invasive breast carcinoma (8); brain tumor (4); heart attacks (4); lung carcinoma (4); lupus (4); meningitis (4); peritonitis (4); Sepsis (4); Stroke (4); virus infection (4); adenocarcinoma (3); Arthritis (3); colon cancer (3); infectious disease (3); ovarian carcinoma (3); astrocytoma (2); autoimmune disease (2); brain ischemia (2); cyst (2); endotoxemia (2); esophageal cancer (2); gastric tumors (2); head and neck cancer (2); hepatocellular carcinoma (2); inflammatory bowel disease (2); injury (2); kidney transplant (2); lymph node metastases (2); lymphoma (2).
A further 83 diseases each share a sentence with F11R in 2 papers or fewer.